PRPF8 (pre-mRNA processing factor 8)
Diseases named in the same sentence as PRPF8 in open-access papers (continued):
Sharing a sentence is not in itself a finding about the gene and the disease.
myelodysplastic syndrome (4 papers, 2016 to 2025). A clonal hematopoietic disorder characterized by dysplasia and ineffective hematopoiesis in one or more of the hematopoietic cell lines. "Studies suggest that PRPF8 mutations can contribute to the development of blood cancers, such as acute myeloid leukemia (AML) and myelodysplastic syndromes." (PMID 40066647, 2025). "Mutations in LUC7L2, PRPF8,SF3B1, SRSF2, U2AF1, and ZRSR2 genes occur at various frequencies ranging between 40% and 85% in different subtypes of myelodysplastic syndrome (MDS) and 5% and 10% of acute myeloid leukemia (AML) and myeloproliferative neoplasms (MPNs)." (PMID 31766606, 2019).
Retinal dystrophy (4 papers, 2021 to 2025). Retinal dystrophy is an abnormality of the retina associated with a hereditary process. "In another family with 3 affected individuals and 1 presumed non-penetrant member, NGS identified three retinal dystrophy genes (PRPF8, PRPH2 and USH2A) with dis-ease-causing variants in varying combinations among the affected individuals." (PMID 40426944, 2025). "Overall, the novel mouse models of aberrant Prpf8 suggest that deregulation of circRNAs could represent a pathological mechanism that co-provokes the retinal dystrophy in splicing factor RP." (PMID 37019475, 2023). "The confirmed genetic diagnosis in the retinal dystrophy group included RP in three (AGBL5, RBP3, and PRPF8), Leber congenital amaurosis in one (RPE65) and gyrate atrophy in one (OAT)." (PMID 33494148, 2021).
Blindness (3 papers, 2016 to 2025). Blindness is the condition of lacking visual perception defined as a profound reduction in visual perception. "Mutations in PRPF8 and SNRNP200 as well as several other splicing factors cause retinal cell degeneration, leading to vision impairment and eventually to blindness." (PMID 40045025, 2025).
prostate carcinoma (3 papers, 2023 to 2025). A carcinoma that arises from epithelial cells of the prostate gland. "PRPF8 interacts with the androgen receptor, regulating its function in prostate cancer cells and controlling its transcriptional activity." (PMID 40136404, 2025). "In prostate cancer, PRPF8 functions as a novel cofactor for the androgen receptor." (PMID 40136404, 2025).
viral infection (3 papers, 2022 to 2025). "The overexpression of PRPF8 enhanced viral replication, while the knockdown of this gene significantly reduced viral production, indicating a positive role of PRPF8 in viral infection." (PMID 40332127, 2025). "For instance, we demonstrated that EFTUD2 and SNRNP200 are required for both apoptosis and necroptosis, whereas EFTUD2 and PRPF8 are required for optimal interferon response against viral infection." (PMID 36560714, 2022). "We demonstrated that EFTUD2 and SNRNP200 are required for both apoptosis and necroptosis, whereas EFTUD2 and PRPF8 are required for optimal interferon response against viral infection." (PMID 36560714, 2022). "In this study, we systemically deciphered the impact of the viral μ2 protein from MRV on transcripts encoding the U5 snRNP proteins EFTUD2, PRPF8, and SNRNP200, in an effort to understand how μ2 triggers a reduction in the level of their corresponding proteins during viral infection." (PMID 36614170, 2022). "The results presented herein highlight novel roles of U5 snRNP proteins EFTUD2, PRPF8, and SNRNP200 in apoptosis, necroptosis, and interferon induction, using MRV as a model for viral infection." (PMID 36560714, 2022). "In this study, we demonstrated distinct and overlapping crucial roles of U5 snRNP core components EFTUD2, PRPF8, and SNRNP200 on apoptosis, necroptosis, and interferon induction during viral infection, using MRV as a model virus." (PMID 36560714, 2022). "In the present study, we deciphered the impact of EFTUD2, PRPF8, and SNRNP200 silencing on viral replication using MRV as a model and discovered novel roles for EFTUD2 and SNRNP200 in cell survival, apoptosis, and necroptosis during viral infection." (PMID 36560714, 2022).
liver cancer (2 papers, 2023 to 2025). An epithelial or non-epithelial malignant neoplasm that arises from the liver. "PRPF8 expression is also associated with the invasiveness of liver cancer cells." (PMID 40136404, 2025). "Indeed, a decrease in PRPF8 expression is associated with reduced aggressiveness of liver cancer cells in vitro and in vivo and with altered expression and splicing patterns of key cancer-related genes." (PMID 36609600, 2023). "Moreover, the loss of PRPF8 significantly inhibits the malignancy of liver cancer cells." (PMID 40136404, 2025). "In liver cancer cells, PRPF8 expression is abnormally elevated and plays a crucial role in liver carcinogenesis by altering FN1 splicing, activating the FAK/AKT pathway, and promoting stress fiber formation." (PMID 40136404, 2025). "PRPF8 expression was silenced in liver cancer cell lines and in xenograft tumors to understand the functional and mechanistic consequences." (PMID 36609600, 2023). "In experiments on human samples, cell lines and animal models, Manuel D. Gahete at the Maimónides Institute of Biomedical Research of Córdoba, Spain, and co-workers investigated the role of PRPF8, a key component of the protein complex that drives the splicing process in liver cancer." (PMID 36609600, 2023). "Silencing the PRPF8 gene decreased tumour growth and aggressiveness, indicating such an approach could prove useful in treating liver cancer." (PMID 36609600, 2023). "Furthermore, upregulation of PRPF8 correlates with poor prognosis in clinical liver cancer patients, acting as a tumor promoter by regulating the PI3K/Akt pathway in hepatic stellate cells and HCC cells, thereby enhancing liver cancer cell viability and metastatic potential." (PMID 40136404, 2025).
lung carcinoma (2 papers, 2021 to 2025). "In lung cancer, a significant difference in PRPF8 expression is observed between cancerous and adjacent tissues, with PRPF8 expression significantly affecting lung cancer cell proliferation and colony formation." (PMID 40136404, 2025). "Additionally, analysis using the ENCORI database and related studies revealed that the stress response of lung cancer cells to chemotherapy is mediated by a reduction in selective splicing events, including those involving PRPF8, leading to decreased gene transcription." (PMID 40136404, 2025).
night blindness (2 papers, 2015 to 2024). Inability to see clearly in dim light. "A 56-year-old asymptomatic carrier (III:7) family member did not complain of night blindness, and fundus examination showed no RP changes in both eyes (data not shown), suggesting incomplete penetrance of the PRPF8 mutation." (PMID 26496393, 2015).
osteosarcoma (2 papers, 2015 to 2017). A usually aggressive malignant bone-forming mesenchymal neoplasm, predominantly affecting adolescents and young adults. "Moreover, U2OS osteosarcoma cells depleted of PRPF8 with two independent siRNAs and monitored by phase-contrast time-lapse microscopy spend >120 min in mitosis, as opposed to control cells, in which mitosis lasts, on average, <60 min." (PMID 26392272, 2015). "First, we examined whether PRPF8 and XAB2 form a complex in the human osteosarcoma U2OS cell line, by performing co-IP analysis." (PMID 29212152, 2017).
ZIKV infection (2 papers, 2017). "It has been demonstrated that ZIKV infection upregulates PRPF8, which is a splicing factor known to have an anti-apoptotic effect in neurons infected with Picornavirus." (PMID 28878777, 2017).
apraxia (1 paper, 2026). Apraxia is a neurological disorder characterized by the inability to perform tasks or movements, despite having the desire and physical ability to perform them. "PRPF8 and TRIO were present in the module previously found enriched for genes linked to childhood apraxia of speech." (PMID 40836029, 2026).
autism (1 paper, 2025). Persistent deficits in social interaction and communication and interaction as well as a markedly restricted repertoire of activity and interest as well as repetitive patterns of behavior. "A bioinformatic analysis of monogenic ID identified PRPF8 as a key hub in gene‐interaction networks linked to autism, epilepsy, and facial dysmorphisms." (PMID 40066647, 2025). "In conclusion, our report suggests a possible novel pattern of inheritance for PRPF8‐related genetic variants that result in craniofacial syndromic features, microcephaly, and NDDs, including autism and ID." (PMID 40066647, 2025).
autism spectrum disorder (1 paper, 2025). A spectrum of developmental disorders that includes autism, and Asperger syndrome. "Recent studies have proposed PRPF8 as a candidate gene associated with developmental delay and autism spectrum disorder (ASD)." (PMID 40066647, 2025). "Emerging evidence suggests PRPF8 plays a role in conditions like autism spectrum disorder ASD and ID." (PMID 40066647, 2025).
carcinoids (1 paper, 2023). "The presence of the selected splicing factors in carcinoids was further examined by IHC analysis, which confirmed that the protein of three splicing factors, NOVA1, PRPF8 and SRSF10 was detectable in tissue samples." (PMID 38049848, 2023). "Inasmuch as the primary known role for NOVA1, PRPF8 and SRSF10 is their function as splicing factors, we aimed at examining their putative relationship with the alternative splicing profile in carcinoid cells." (PMID 38049848, 2023).
colorectal cancer (1 paper, 2025). A primary or metastatic malignant neoplasm that affects the colon or rectum. "This review provides an in-depth analysis of the mechanisms by which PRPF8 regulates tumorigenesis through AS, exploring its role in diverse cancer types, including breast, liver, myeloid, and colorectal cancers." (PMID 40136404, 2025).
glaucoma (1 paper, 2018). Increased pressure in the eyeball due to obstruction of the outflow of aqueous humor. "In the current study, we identified mutations located at the N-terminus of PRPF8 associated with glaucoma." (PMID 28707069, 2018).
glioma (1 paper, 2022). A benign or malignant brain and spinal cord tumor that arises from glial cells (astrocytes, oligodendrocytes, ependymal cells). "To test this hypothesis, we transfected glioma cells with the miR-10b antisense oligonucleotide (ASO) inhibitor and examined the effects of miR-10b KD on the U6 association with SART3 and PRPF8 using iCLIP." (PMID 35033060, 2022). "Of note, nuclear Ago2 was observed in glioma cells and both SART3 and PRPF8 were pulled-down by the Ago2 immunoprecipitation." (PMID 35033060, 2022).
hyperglycaemia (1 paper, 2021). "Studies from our laboratory using in vitro models mimicking different obesogenic inputs (hyperglycaemia/hyperinsulinemia, adipocyte hypertrophy, inflammation) failed to modify PRPF8 mRNA levels in preadipocytes (data not shown)." (PMID 34545810, 2021).
influenza infection (1 paper, 2022). "PRPF8 has previously been demonstrated to influence viral replication, as during influenza infection, it is induced by viral proteins and act as a proviral factor increasing viral production." (PMID 35489070, 2022).
kidney damage (1 paper, 2025). "For example, differential methylation of PQLC2, PTPN6/PHB2, and PRPF8 has been reported to be associated with fibrosis and inflammation leading to kidney damage." (PMID 41357321, 2025).
leukemia (1 paper, 2021). A malignant (clonal) hematologic disorder, involving hematopoietic stem cells and characterized by the presence of primitive or atypical myeloid or lymphoid cells in the bone marrow and the blood. "PRPF8 is the only U5 snRNP protein where recurrent somatic mutations have been linked to cancer, joining the ranks of spliceosome factors such as U2AF1 and SF3B1 as frequently mutated in certain types of human cancers, in particular leukemias." (PMID 33584830, 2021).
lung carcinoids (1 paper, 2023). "In summary, our work primarily unveils a clear alteration of the splicing machinery in lung carcinoids that is linked to three specific factors, NOVA1, PRPF8 and SRSF10, which are differentially associated to pathological features, distinct profiles of splicing events, and key functional actions." (PMID 38049848, 2023).
macular cysts (1 paper, 2021). "The presence of macular cysts and the retinal phenotype observed in affected twins is more consistent with the phenotype associated with PRPF31 than with PRPF8." (PMID 34662339, 2021).
mastitis (1 paper, 2022). Inflammation of breast tissue during lactation or postpartum due to an obstructed duct or infection. "Furthermore, SNP rs133847062 on chromosome 19 at 22,777,382bp of gene PRPF8 had the genotype AC in healthy cows and AA in subclinical mastitis cows." (PMID 36204322, 2022). "In our study, a total of 32 AS SNPs were identified, of which two SNPs rs42705933 and rs133847062 had completely different genotypes between healthy cows and subclinical mastitis cows, which corresponded to SE events of PIK3C2B and PRPF8." (PMID 36204322, 2022).
Obesity (1 paper, 2021). Accumulation of substantial excess body fat. "(C) mRNA levels of PRPF8 in SC and OM preadipocytes from lean, and NG and T2D subjects with simple obesity (cohort 2; n = 5–11, 1 technical replicate each)." (PMID 34545810, 2021). "We employed a siRNA strategy to down-regulate PRPF8 gene expression levels in preadipocytes to mimic the conditions found in IR/T2D obese SC preadipocytes as compared to NG obesity." (PMID 34545810, 2021).
Parkinson disease (1 paper, 2024). A progressive degenerative disorder of the central nervous system characterized by loss of dopamine producing neurons in the substantia nigra and the presence of Lewy bodies in the substantia nigra and locus coeruleus. "PRPF8 currently has no obvious connection to AD, however, it was one of 10 genes found to be associated with AD and Parkinson’s disease in another study involving a different dataset (GSE4229) using an alternative tissue: peripheral blood." (PMID 39309755, 2024).
primary open angle glaucoma (1 paper, 2021). "Mutations in PRPF8 have been implicated in the development of adRP and primary open angle glaucoma (POAG)." (PMID 34395430, 2021).
Rod-cone dystrophy (1 paper, 2023). An inherited retinal disease subtype in which the rod photoreceptors appear to be more severely affected than the cone photoreceptors. "The PRPF8:c.5506-11_5506-10del variant was found in a sporadic individual diagnosed with rod cone dystrophy." (PMID 38076877, 2023).
triple-negative breast carcinoma (1 paper, 2020). An invasive breast carcinoma which is negative for expression of estrogen receptor (ER), progesterone receptor (PR), and human epidermal growth factor receptor 2 (HER2). "Moreover, in triple-negative breast cancer cells, the expression of proteasomal genes PSMB4 and PSMB5 was dependent on the expression of splice factors PRPF8 and PRPF38A." (PMID 32545483, 2020).
cancer (14 papers, 2017 to 2025). A tumor composed of atypical neoplastic, often pleomorphic cells that invade other tissues. "Mutations and/or alterations in the expression of PRPF8 proteins in cancers have been implicated in the dysregulation of pre-mRNA splicing, thereby promoting tumorigenesis." (PMID 40136404, 2025). "An increasing number of studies confirm that alterations in the AS process mediated by PRPF8 are associated with various cancers." (PMID 40136404, 2025). "This suggests that, compared to low-risk MDS, PRPF8 mutations are associated with more aggressive cancer phenotypes." (PMID 40136404, 2025). "Disruptions in PRPF8 function are linked to a variety of cancers, as mutations in this gene can induce abnormal splicing events that contribute to tumorigenesis, metastasis, and drug resistance." (PMID 40136404, 2025). "Understanding the molecular mechanisms by which PRPF8 mutations contribute to cancer progression will provide valuable insights into the development of novel cancer therapies." (PMID 40136404, 2025). "PRPF8 overexpression directly influences cancer aggressiveness and alters cancer-related splicing variants, particularly fibronectin 1, a glycoprotein found in the extracellular matrix." (PMID 36609600, 2023). "We also revealed that the modulation of PRPF8 leads to alterations in the expression and splicing patterns of numerous genes implicated in different key cancer-related pathways (cell cycle, proliferation, etc.)." (PMID 36609600, 2023). "One can postulate that RP-associated variants and cancer-linked somatic mutations affect different aspects of PRPF8 function, although RP PRPF8 variants can affect both spliceosome assembly and SNRNP200 regulation (Ru°žičková and Staněk, 2017)." (PMID 33584830, 2021). "The identification of "hot spots" within the PRPF8 gene that are frequently mutated across cancer types could offer insights into therapeutic strategies aimed at restoring proper splicing patterns." (PMID 40136404, 2025). "Furthermore, we examine the molecular pathways associated with PRPF8 dysregulation and their impact on cancer progression." (PMID 40136404, 2025). "A pan-cancer analysis revealed the alteration landscape of spliceosome genes across 27 cancer types in 9070 patients, demonstrating both common and specific changes in spliceosome genes among different cancer types, with PRPF8 showing a high mutation rate (7%)." (PMID 40136404, 2025). "In cancer cells, however, the function of PRPF8 may be altered due to mutations, leading to the production of abnormal splicing isoforms of genes that regulate critical pathways." (PMID 40136404, 2025). "However, the mechanisms through which different mutations and/or varying expression levels of the same PRPF8 gene lead to contrasting phenotypes, such as retinal or craniofacial defects and cancer, remain enigmatic." (PMID 40136404, 2025). "Although mutations in the PRPF8 gene are frequently observed in various cancers through TCGA database analyses, the mechanisms underlying the splicing errors in the diverse gene subgroups regulated by PRPF8 remain unclear." (PMID 40136404, 2025). "PRPF8 is the core protein of splicing, the mutation of PRPF8 could cause the death of model cell, and it has an important relationship with the occurrence of the disease particularly in cancer." (PMID 32690086, 2020). "Moreover, to address these challenges, next-generation sequencing and RNA-Seq could be utilized to identify the full spectrum of splicing alterations caused by PRPF8 mutations in various cancer types will reveal novel biomarkers and therapeutic targets." (PMID 40136404, 2025). "Exactly, previous studies have shown that PRPF8, SPAG7, SENP3 and GPS2 are associated with the occurrence of various cancers." (PMID 40015977, 2025). "We also discuss the emerging potential of targeting PRPF8 in cancer therapy, highlighting challenges in drug development." (PMID 40136404, 2025).